PFKP (phosphofructokinase, platelet)
Diseases named in the same sentence as PFKP in open-access papers (continued):
Sharing a sentence is not in itself a finding about the gene and the disease.
renal fibrosis (3 papers, 2023 to 2026). A final common manifestation of a wide variety of chronic kidney diseases characterized by glomerulosclerosis and tubulointerstitial fibrosis. "Research has demonstrated that PFKP overexpression in proximal renal tubular epithelial cells exacerbates glycolysis and renal fibrosis triggered by TGF-β." (PMID 41393259, 2025). "We overexpressed PFKP in UUO mouse kidneys and treated them with 2-DG to observe the effect of PFKP overexpression on renal fibrosis under conditions of glycolysis inhibition." (PMID 38086793, 2023). "Additionally, qRT‐PCR analysis revealed a significant increase in the expression of HK2 and PFKP, key genes involved in the hypoxia response, underscoring the metabolic reprogramming that contributes to renal fibrosis under heat stress." (PMID 41573374, 2026). "Furthermore, inhibition of glycolysis and PFKP expression by ISO ameliorated renal fibrosis." (PMID 38086793, 2023). "In line with this, in the present study, we found that overexpression of PFKP in PTECs exacerbates TGF-β-induced glycolysis and renal fibrosis, while knocking down PFKP attenuates PTECs glycolysis and renal fibrosis in vitro and in vivo." (PMID 38086793, 2023). "In the present study, we found that ISO could inhibit the expression of PFKP and decrease glycolysis and renal fibrosis in UUO mice, suggesting that ISO may be a new treatment strategy for renal fibrosis." (PMID 38086793, 2023). "First, we did not validate the role of PFKP in other renal fibrosis models, such as folic acid-induced AKI models and unilateral renal ischemia-reperfusion models." (PMID 38086793, 2023). "Notably, based on the expression of fibrosis-related genes, Masson and Sirius Red staining, we found that the combined treatment of PFKP + 2-DG did not significantly induce renal fibrosis compared to UUO mice treated with AAV-ctrl and vehicle." (PMID 38086793, 2023).
T-cell acute lymphoblastic leukemia (3 papers, 2023 to 2025). Acute lymphoblastic leukemia of T-cell origin. "For example, previous report indicated that PFKP serves as a nucleocytoplasmic shuttling protein, with nuclear PFKP capable of interacting with c-Myc, thereby stabilizing it and enhancing its activity in T-cell acute lymphoblastic leukemia." (PMID 38982480, 2024).
bladder cancer (2 papers, 2020 to 2022). "Furthermore, when PFKP inhibitor 2,5-anhydro-D-glucitol-6-phosphate was employed in T24 bladder cancer cells, the cell growth was significantly decreased via suppression of glycolysis." (PMID 32470015, 2020).
cardiac hypertrophy (2 papers, 2025). "Additionally, we found that Gen-miR-5 derived from G. acuta alleviates cardiac hypertrophy by targeting PFKP; however, its underlying mechanisms in inhibiting MF remain unclear." (PMID 40385478, 2025). "It has been reported that inhibiting PFKP can downregulate BNP expression and protein synthesis during myocardial hypertrophy, thereby alleviating cardiac remodeling." (PMID 40385478, 2025).
COVID-19 (2 papers, 2021 to 2022). A disease caused by infection with severe acute respiratory syndrome coronavirus 2. "The only pathway that was significantly downregulated in COVID-19 monocytes was glycolysis, with decreased expression of a number of enzymes involved in glucose degradation, including PFKP, ENO1, PFKB4 and others." (PMID 36572683, 2022). "After comparing the collected genes, 460 host factors common to COVID-19 and dengue were found, including MMP2, PDF, PFKP, SLC25A3, IGF1, CCL4, TLR4, and AhR, and further analysis of interaction networks was performed." (PMID 34394108, 2021).
gastric cancer (2 papers, 2021 to 2023). A primary or metastatic malignant neoplasm involving the stomach. "We then verified the protein profile results by western blotting assay and found that gastric cancer exosomes contained key enzymes of the glycolysis pathway, such as PKM2, LDHA, and PFKP." (PMID 33731686, 2021).
head and neck squamous cell carcinoma (2 papers, 2024 to 2026). A squamous cell carcinoma that arises from any of the following anatomic sites: lip and oral cavity, nasal cavity, paranasal sinuses, pharynx, larynx, and salivary glands. "However, the precise molecular mechanisms underlying the role of PFKP in head and neck squamous cell carcinoma (HNSCC) are not fully elucidated." (PMID 38982480, 2024).
kidney cancer (2 papers, 2016 to 2023). Primary or metastatic malignant neoplasm involving the kidney. "Therefore, our data have revealed a novel role of PFKP in regulating kidney cancer cell metabolism and proliferation and uncovered the underlying mechanism." (PMID 27049827, 2016). "As expected, PFKP knockdown reduced glucose uptake and lactate production per cell in all three kidney cancer cell lines, indicating declined aerobic glycolysis." (PMID 27049827, 2016). "We next assessed the effect of PFKP knockdown on kidney cancer cell proliferation." (PMID 27049827, 2016). "Since PFKP was required for cell proliferation in kidney cancer cell lines, we next investigated whether PFKP was sufficient for promoting cell proliferation in low PFKP-expressing HK-2 cells." (PMID 27049827, 2016). "Cellular ATP levels were similar in kidney cancer cells transfected with control or PFKP siRNAs." (PMID 27049827, 2016). "Decreased PFKP expression inhibited aerobic glycolysis, PPP and nucleotide biosynthesis while increased TCA cycle activity in kidney cancer cells." (PMID 27049827, 2016). "Our results suggest that PFKP suppression decreased glycolytic activity and induced oxygen consumption without affecting cellular energy status in kidney cancer cells." (PMID 27049827, 2016). "Knockdown of PFKP, but not PFKL or PFKM, inhibited kidney cancer cell growth and induced apoptosis and cell cycle arrest." (PMID 27049827, 2016).
lymphoma (2 papers, 2022 to 2024). A malignant (clonal) proliferation of B- lymphocytes or T- lymphocytes which involves the lymph nodes, bone marrow and/or extranodal sites. "Additionally, the ChIP-seq data and RNA-seq data from public databases (GSE138295, GSE126739) revealed that c-Myc has a significant signal in the promoter region of PFKP, and the PFKP mRNA levels were significantly reduced after reduction of c-Myc in lymphoma cells." (PMID 38982480, 2024). "Recently, nuclear phosphofructokinase, platelet (PFKP) was reported to stimulate CXCR4 expression through c‐MYC activity in T‐ALL and lymphoma cells." (PMID 36054080, 2022).
metastatic tumors (2 papers, 2024 to 2025). "PFKP (locus: 10p15.2) was positively associated with the development of metastases, whereas the ZBTB20 gene (locus: 3q13.31) was downregulated in the metastatic tumors (p-raw < 0.05)." (PMID 38673877, 2024). "The genes that were upregulated in the monosomy 3/metastatic tumors (PFKP, NUP88) exhibited an average fold change (FC) of 2.06 ± 0.82, whereas the downregulated genes (INSR, RBKS, and ZBTB20) differed by an average of −1.87 ± 0.44-fold." (PMID 38673877, 2024). "Therefore, we revealed a significantly higher expression of PFKP and Ki67 (p < 0.0001 and p < 0.0001) genes in metastatic tumors." (PMID 40821334, 2025).
pulmonary arterial hypertension (2 papers, 2025). Pulmonary arterial hypertension (PAH) is a group of diseases characterized by mean pulmonary artery pressure >20 mmHg and elevated pulmonary arterial resistance leading to right heart failure. "PFKP expression is significantly elevated in pulmonary arterial hypertension patient SMCs and hypertrophic cardiomyocytes." (PMID 41421488, 2025).
Stroke (2 papers, 2022 to 2026). Sudden impairment of blood flow to a part of the brain due to occlusion or rupture of an artery to the brain. "In contrast, SLC16A1, SIRT3, PFKP, and TKT were inversely associated with stroke risk, suggesting a potential protective role." (PMID 41877258, 2026).
autism (1 paper, 2025). Persistent deficits in social interaction and communication and interaction as well as a markedly restricted repertoire of activity and interest as well as repetitive patterns of behavior. "The PM3 model revealed suppressed glycolytic flux in the autism cortex, with a reduced expression of key enzymes such as PFKP and PKM2." (PMID 40559423, 2025).
bipolar disorder (1 paper, 2024). A disorder of the brain that causes unusual shifts in mood, energy, activity levels and the ability to carry out day-to-day tasks. "ENO1, PFKP, and GAPDH were also downregulated in bipolar disorder with a similar magnitude of expression change in both states." (PMID 39125835, 2024). "In bipolar disorder, most glycolytic genes were downregulated, which included PFKM, PFKP, and PFKL, providing support for decreased glycolytic flux, but the magnitude of gene expression change was greater among the upregulated genes." (PMID 39125835, 2024).
depression (1 paper, 2024). "PFKP showed a discordant expression pattern, as it was upregulated in major depressive disorder but downregulated in ketosis." (PMID 39125835, 2024). "In major depressive disorder, a greater number of glycolytic genes were upregulated, which included PFKP, providing support for increased glycolytic flux in major depressive disorder; however, the magnitude of gene expression change was greater among the downregulated genes." (PMID 39125835, 2024).
endometrioid carcinoma (1 paper, 2021). "GLUT1, MCT4, PFKP, PGK1, and PKM2 had lower expression levels in endometrioid carcinoma." (PMID 34277429, 2021).
heart failure (1 paper, 2023). Inability of the heart to pump blood at an adequate rate to meet tissue metabolic requirements. "Inhibition of PFKP was able to block the expression of Nppb, a marker of CM remodeling and heart failure." (PMID 37938421, 2023). "In summary, elevated PKFP activity and expression are important factors contributing to heart failure, and inhibition of PFKP alleviates the stress response of CM and attenuates cardiac rational remodeling." (PMID 37938421, 2023). "This suggests that PFKP is involved in the stress response in CM and is a new heart failure-inducible gene." (PMID 37938421, 2023).
intrahepatic cholangiocarcinoma (1 paper, 2025). A carcinoma that arises from the intrahepatic bile duct epithelium in any site of the intrahepatic biliary tree. "A recent study demonstrated that in intrahepatic cholangiocarcinoma, the overexpression of PFKP and the activation of AMPK resulted in IDH1 mutation in normal biliary cells." (PMID 40821334, 2025).
melanoma (1 paper, 2016). A malignant, usually aggressive tumor composed of atypical, neoplastic melanocytes. "Together with our recent demonstration of ABCB5-mediated regulation of IL-1β secretion in human melanoma cells, these results suggest that the glycolysis pathway in melanoma cells is potentially regulated by an ABCB5/IL-1β/HIF-1α/PFKP signaling cascade." (PMID 27560924, 2016).
migraine (1 paper, 2023). "We also found upregulation of PFKP, a key enzyme of the glycolytic pathway, thus indicating an enhancement of glycolysis in a rat model of migraine." (PMID 37090989, 2023). "In the medullary dorsal horn of the experimental migraine model, the key glycolysis enzyme PFKP (2.09 ± 0.32) was significantly higher than that in the control group (1.10 ± 0.38)." (PMID 37090989, 2023). "In the experimental model of migraine, key enzymes involved in glycolysis such as phosphofructokinase platelet (PFKP), hexokinase (HK2), hypoxia inducible factor-1α (HIF-1α), lactate dehydrogenase (LDH) and pyruvate kinase (PKM2) were expressed in the medullary dorsal horn." (PMID 37090989, 2023). "To explore whether glycolysis increased during the experimental models of migraine, we detected the gene expression of important enzymes related to glycolysis, such as PFKP, HK2, HIF-1α, LDH and PKM2." (PMID 37090989, 2023). "Compared with CON group, quantitative real-time polymerase chain reaction showed that PFKP (2.02 ± 0.51), HK2 (2.55 ± 0.72), HIF-1α (3.05 ± 0.61) and PKM2 (1.97 ± 0.49) mRNA expression increased in migraine model group." (PMID 37090989, 2023).
mucinous carcinoma (1 paper, 2021). "In addition, GLUT1, HK2, PFKP, PGK1, and PKM2 had higher expression levels in mucinous carcinoma." (PMID 34277429, 2021).
neuroblastoma (1 paper, 2021). Neuroblastoma (NB) is the most common solid, extracranial childhood tumor. "Other proteins linked to metabolism such as eEF2, PFKP, GAPDH and ribosomal protein L10a were also confirmed to be enriched in the EVs secreted by MYCN-positive neuroblastoma cells." (PMID 34847775, 2021).
Pan (1 paper, 2022). "Additionally, the expression of the glycolysis rate-limiting genes HK2, PFKP and PKM2 showed expression patterns similar to non-rate-limiting genes in the Pan Cancer TCGA cohort." (PMID 36505421, 2022).
pulmonary disease (1 paper, 2022). "PFKP, the platelet type of PFK, influences the respiratory system by regulating glycolysis and plays a central role in the progression of pulmonary disease under hypoxic condition." (PMID 35450040, 2022).
pulmonary fibrosis (1 paper, 2020). Chronic progressive interstitial lung disorder characterized by the replacement of the lung tissue by connective tissue, leading to progressive dyspnea, respiratory failure, or right heart failure.
schizophrenia (1 paper, 2024). A major psychotic disorder characterized by abnormalities in the perception or expression of reality. "In glycolysis, the gene ENO1 showed a discordant expression pattern between the two groups (i.e., ENO1 was upregulated in schizophrenia and downregulated in ketosis), whereas the genes GAPDH and PFKP showed a concordant expression pattern, being downregulated in both states." (PMID 39125835, 2024).
Ureteral obstruction (1 paper, 2023). Obstruction of the flow of urine through the ureter. "To investigate the potential involvement of PFKP in the pathogenesis of kidney fibrosis, we first determined its protein expression levels in fibrotic mouse kidney tissues induced by unilateral ureteral obstruction (UUO)." (PMID 38086793, 2023).
viral infection (1 paper, 2024). "When we knocked down or overexpressed FBP1 or PFKP to regulate the consumption and production of endogenous FBP, we observed that the concentrations of endogenous FBP influenced viral infection." (PMID 39693295, 2024). "PFKP knockdown produced similar effects, reinforcing the connection between FBP levels and viral infection." (PMID 39693295, 2024).
tumor (83 papers, 2013 to 2026). "Elevated PFK1 expression, particularly the PFKP isoform, is often linked to enhanced glycolysis, tumour growth, and resistance to therapies, making it a potential target for cancer treatment strategies." (PMID 41154605, 2025). "Association of clinicopathological characteristics with PFKP expression in control and tumor samples." (PMID 40821334, 2025). "Since PFKP is associated with tumor angiogenesis in cancers, we explored its role in the vascular formation capacity of HNSCC cells." (PMID 38982480, 2024). "PFKP was also positively associated with tumor diameter and extrascleral extension whereas the tumors with ZBTB20 deficiency exhibited a more diffuse rather than focal pattern of macrophage infiltration." (PMID 38673877, 2024). "Of note, PFKP isoform is frequently highly expressed in lung cancer tissues and cell lines, and it is associated with tumor size and patient prognosis." (PMID 35626081, 2022). "Moreover, we observed an association of PFKP expression with Ki67, a biomarker for tumor metastasis, and calculated the Chi-squared value (42.85), showing a highly significant p-value (<0.0001)." (PMID 40821334, 2025). "Previous studies have demonstrated that elevated PFKP activity in GBMs and other solid tumors is associated with increased glycolytic metabolism and is required for the proliferation and tumorigenesis of tumor cells." (PMID 30250190, 2018). "Interestingly, transient loss of PFKP during an initial period in quantities that generated suboptimal engraftment significantly enhanced in vivo tumour initiation." (PMID 28176759, 2017). "Interestingly, most of protective genes were downregulated in tumor tissue except for PFKP, suggesting that their deficiency might contribute to the initiation, development, and prognosis of KIRC." (PMID 37553601, 2023). "Our bioinformatic analysis revealed a marked reduction in PHGDH expression in tumor tissues, which shows a strong positive correlation with PFKP expression." (PMID 41333208, 2025). "In the current study, we further investigated the network of genes related to PFKP in promoting tumor metastasis." (PMID 40821334, 2025). "This switch was associated with increased glycolytic activity in tumour cells, highlighting the potential role of cancer-specific PFK1 isoform, predominantly PFKP, in clinical diagnosis." (PMID 41154605, 2025). "The key finding of the current study is that PFKP is upregulated in all cohorts (discovery and validation) regarding tumor, control, and metastasis." (PMID 40821334, 2025). "PFKP-mediated expression of other glycolytic gene conditions is imperative to support the tumor microenvironment to promote metastasis." (PMID 40821334, 2025). "In summary, while research on cuproptosis-related genes in LUAD is still evolving, C1QBP and PFKP appear to play significant roles in tumor progression." (PMID 41041346, 2025). "The overexpression of PFKP in cancer cells promotes increased glucose uptake and enhanced glycolysis, providing the necessary energy and metabolic substrates for tumor growth and survival." (PMID 40821334, 2025). "The results showed that PFKP inhibition significantly suppressed tumor growth, tumor volume, and tumor weight." (PMID 38217030, 2024). "The suppression of PFKP markedly inhibited tumor growth compared to the control, as reflected by the decreased tumor volume and lower tumor weight in the PFKP-knockdown group compared to that in the control group." (PMID 38982480, 2024). "We assessed the expression levels of PFKP and c-Myc in tumor and adjacent normal tissues from 120 HNSCC patients." (PMID 38982480, 2024). "Consistent with our in vitro results, c-Myc re-expression abolished the suppressive effects of PFKP depletion on xenograft growth and tumor angiogenesis." (PMID 38982480, 2024). "It is more likely that other regulatory mechanisms are involved in the regulation between PFKP and c-Myc across different tumor types." (PMID 38982480, 2024).